TNF (tumor necrosis factor)
Diseases named in the same sentence as TNF in open-access papers (continued):
Sharing a sentence is not in itself a finding about the gene and the disease.
Sepsis (continued). "We chose to deplete TNFR1 in cells (i) which are known to respond strongly to TNF, for example after TNF injection and (ii) which are believed to play a role in sepsis, namely IECs, endothelial cells and hepatocytes." (PMID 31787972, 2019). "Interleukin-1, discovered in 1971, and tumor necrosis factor, discovered in 1975, were among the earliest cytokines identified; they were then found to play central roles in sepsis pathophysiology." (PMID 31892321, 2019). "Clinical sepsis data regarding the relationship between TNFα concentration and sepsis mortality are conflicting." (PMID 31297113, 2019). "Because the nature of sepsis is an excessive inflammatory response to infection,we measured serum pro-inflammatory cytokine levels including TNF-α, IL-1β andIL-6." (PMID 30843942, 2019). "α-1-antichymotrypsin also acts as a negative regulator of pro-inflammatory cytokine production (e.g., TNF-α and IL-1β) and innate immunity, thus protecting against systemic inflammation (i.e., lethal endotoxemia and sepsis)." (PMID 31001142, 2019). "The levels of leptin seem to rapidly increase in acute inflammatory conditions, such as cholecystectomy and sepsis, particularly favored by cytokines such as TNF-α, IL-6, and IL-1β." (PMID 30949073, 2019). "In sepsis, the decrease in endothelial barrier function by lipopolysaccharide (LPS) and tumor necrosis factor (TNF) α increases microvascular permeability and contributes to multi-organ failure and death." (PMID 31174369, 2019). "The balance between TNF- activity and sTNF-Rs determines the course of immune activation and inflammatory response, and its dysregulation may play a role in susceptibility and resistance to various diseases, including sepsis, cancers, as well as autoimmune and inflammatory diseases." (PMID 30911316, 2019). "We reasoned based on literature that the most obvious candidate cells that would suffer the most from TNF in this model and sepsis in general would be the intestinal epithelial cells (IECs), endothelial cells and hepatocytes." (PMID 31787972, 2019). "And its low expression was associated with advanced disease severity (APACHE II score and SOFA score) and systemic inflammation (CRP, PCT, TNF‐α, IL‐1β, IL‐6, and IL‐17) in sepsis patients." (PMID 31206807, 2019). "In fact, serum IL-10 concentrations were demonstrated in a human clinical study to correlate well with the sepsis severity and mortality, as also did the high IL-10/TNF-α ratio." (PMID 31075981, 2019). "High concentrations of TNF-α, an inflammatory cytokine, occur along with inflammation, injury, sepsis and some infections." (PMID 30657773, 2019). "This was associated with lower levels of key inflammatory cytokines in the acute phase of sepsis including IL-6, TNF-alpha in response to CX43 blockade or deletion." (PMID 30735126, 2019). "We measured cytokine expression and production of IL-6, TNF-α and IFN-β in Ets2 knockdown or knockout macrophages and susceptibility to cecal ligation and puncture (CLP)-induced sepsis in Ets2-deficient mice." (PMID 31785145, 2019). "In sepsis, high levels of proinflammatory cytokines, particularly TNFα have been thought to increase endothelial cell permeability, which can hinder cells from obtaining necessary nutrients." (PMID 31801287, 2019). "Serum cytokines, including IL6, IFNγ, IL1β, IL10, and TNFα were high suggesting the onset of sepsis in most of these mice even though there was a high degree of variation of bacterial load." (PMID 31121001, 2019). "Release of pro-inflammatory cytokines, particularly TNF-a, IL-6 is an important component of the host immune response and the role of these molecules in the pathogenesis of sepsis has been well studied." (PMID 30820191, 2019). "Erastin administration increased the survival rate in mice upon sepsis induction, followed by a reduction in inflammatory mediators and cytokines, including NO, TNF-α, and IL-1β." (PMID 31847346, 2019).
Sepsis (continued). "In vivo, intravenous injection of histones in mice was lethal, whilst anti-histone antibodies were found to reduce mortality in murine models of LPS endotoxemia, TNF-α, or cecal ligation, and puncture experimental models of murine sepsis." (PMID 31736963, 2019). "TNF had significant Z scores for one DLE and one WB SLE dataset; the highest Z score for TNF was obtained with the control sepsis dataset." (PMID 31044165, 2019). "NO and proinflammatory cytokines including IL-1β and TNF-α were involved in LPS induced inflammation of macrophages, which mimic the clinical sepsis-induced inflammatory responses." (PMID 31856816, 2019). "Sepsis severity was evaluated by murine sepsis scores, blood bacterial load, plasma tumor necrosis factor-α [TNF-α]/interleukin-6 [IL-6] levels and histopathology of vital organs." (PMID 31501504, 2019). "Clinical trials of anti-TNF therapy have shown little beneficial impact in acute inflammatory diseases such as sepsis or ARDS despite ample preclinical evidence of TNF involvement in their pathophysiology." (PMID 30776316, 2019). "Another important cytokine during sepsis in humans and horses is IL-6, which is produced after cells are exposed to TNFα and IL-1β." (PMID 30931316, 2019). "Early attempts to modulate immune responses in sepsis included an injection of antibodies that neutralize TNF-α; with these antibodies, favorable results were obtained in animal studies, but most of the antibodies failed in clinical phase III trials." (PMID 31671729, 2019). "Patients in the early stages of sepsis showed higher concentrations of TNF, IL-1β, and IL-6 than healthy controls and they had an elevated activation of the proinflammatory transcription factor NFκB in blood leukocytes." (PMID 31072006, 2019). "In the present study, we observed that FX can significantly inhibit the production of inflammatory cytokines IL-6, IL-1β, and TNF-α and promote the sepsis mouse model survival rate from 0% to 40% for the first time." (PMID 31555126, 2019). "Our study indicated that the serum cytokines such as TNF-α, IL-1β, and IL-6 were inhibited by hydrocortisone, which were consistent with previous studies in both animals and humans with sepsis." (PMID 31880211, 2019). "In this study, we chose LPS and TNF-α as a typical example of an endotoxin produced by Gram-negative bacteria, and a main mediator of pro-inflammatory cytokines release during sepsis, respectively." (PMID 30778043, 2019). "Wild type (WT) mice treated with poly(I:C) exhibited altered expression patterns of TNF and IL-12p40 during CASP which were dependent on IFNβ or IFNAR1, suggesting a mechanism for the increased sepsis susceptibility of WT mice." (PMID 31500303, 2019). "Phospholipase D1 is a regulator of tumor necrosis factor-α expression and release upon LPS-induced sepsis and following myocardial infarction (MI)." (PMID 30555342, 2018). "Equilibrium between TNF-α, IL-1β and anti-inflammatory IL-10 has been proven highly dynamic and dependent on genetic heterogenity in human sepsis and SIRS." (PMID 29304171, 2018). "Consistent with a prior report, splenocytes isolated from sepsis surviving mice were responsive to LPS stimulation showing increased secretion of TNFα compared to splenocytes from control mice when stimulated with LPS ex vivo." (PMID 30237803, 2018). "In this kinetic experiment, we measured serum levels of proinflammatory cytokines (TNF-alpha, IL-6) that are highly elevated in sepsis." (PMID 30525057, 2018). "Tumor necrosis factor-α and IL-6 are secreted as initial proinflammatory cytokines in sepsis, stimulating the production of thrombopoietin." (PMID 29381746, 2018). "Ulinastatin has been evaluated as a promising drug in the treatment of sepsis, due to the inhibition of various serine proteases, inflammatory mediators produced by neutrophils, and the production of TNF-α, IL-1, and IL-6." (PMID 29467017, 2018).
Sepsis (continued). "Here, we demonstrate that omega-9 treatment is associated with increased levels of the anti-inflammatory cytokine IL-10 and decreased levels of the proinflammatory cytokines TNF-α and IL-1β in peritoneal lavage fluid of mice with sepsis." (PMID 30538802, 2018). "TNF-α, interleukin-1β (IL-1β), IL-6, and monocyte chemotactic protein-1 (MCP-1) are hallmark inflammatory mediators of sepsis that constitute the cytokine storm." (PMID 29980671, 2018). "Ghrelin suppressed the release of IL-6 and TNF-α in the peritoneal cavity and the lungs in a sepsis model and in the brain in a focal cerebral ischaemia model in rats through a mechanism that requires intact vagus nerves." (PMID 29593559, 2018). "Gram-negative bacteria endotoxin (lipopolysaccharide, LPS) is known to induce myocardial dysfunction in vitro, in experimental or human sepsis, partly by excessive production of tumor necrosis factor (TNF)-α and IL-1β5,7–9." (PMID 30279549, 2018). "Systemic administration of LPC protects mice against experimental sepsis-induced lethality, enhances bacterial clearance, and inhibits the production of pro-inflammatory cytokines, including TNF-α and IL-1β." (PMID 29755479, 2018). "In severely burned patients with sepsis, plasma levels of endotoxin and cytokines, including TNF-α, IL-1β, IL-6, and IL-8 after CRRT were significantly reduced based on those before the therapy." (PMID 29649247, 2018). "Candidate gene studies for traumatic patients identified several SNPs in lipopolysaccharide-binding protein (LBP), toll-like receptor 1(TLR1), and tumor necrosis factor-alpha (TNF-α) which were related to the development of sepsis." (PMID 30479651, 2018). "In relation to the systemic profile, a significant increase was observed in the levels of TNF, IL-6, and IL-10 in animals of the sepsis group compared to the control (respectively)." (PMID 30524657, 2018). "For example, in sepsis, tumor necrosis factor α (TNFα) is predominantly expressed in the liver, spleen, and lungs by Kupffer cells, leukocytes, and lung epithelial and immune cells, respectively." (PMID 29850639, 2018). "Our data revealed that PLD1 is a key regulator of TNF-α expression upon sepsis because PLD1 plays a major role in the MEK-ERK1/2 mitogen-activated protein kinase (MAPK) pathway upon LPS induction of TNF-α gene expression." (PMID 29968773, 2018). "The lipoxin A4 agonist, BML-111, alters the expression of TLR2 and 4 in a murine cecal ligation/puncture model of sepsis with improvements in pro-inflammatory IL-6 and TNF-α production." (PMID 29515999, 2018). "In fact, toxicity exerted by TNF-α is blunted by endogenous serum leptin, which promotes a protective effect during systemic inflammation, such as sepsis." (PMID 30618812, 2018). "Here, we present a case of Strongyloides hyperinfection in a 75-year-old male secondary to sepsis and chronic immunosuppression due to TNF-α inhibitors." (PMID 30002936, 2018). "As such, studies on Ripk3-deficient mice showed protective effects in models of TNF-induced SIRS and sepsis." (PMID 29606984, 2018). "This study showed that the effects of IL-6 were independent from the effects of TNF-α, IL-1β, and IL-12, but IL-6 was regulated by ILT4, which was associated with poor prognosis of sepsis." (PMID 29662678, 2018). "This study’s novel longitudinal comparison of systemic cytokines in the two separate models demonstrated that the addition of sepsis crosses predictive threshold of IL-6, IL-10, and TNF for immune dysregulation." (PMID 29849508, 2018). "HMGB1 acts as a pro-inflammatory cytokine mediator of sepsis; however, it induces a weak tumor necrosis factor (TNF)-α production in in vitro treatments." (PMID 29696019, 2018). "The knockdown of Beclin1 has been shown to attenuate HMGB1-mediated release of TNF-α and IL-6 in lethal sepsis via inhibiting NF-kB18." (PMID 30478280, 2018).
Sepsis (continued). "The aim of this study was investigate the possible effects of NF-κB1 -94 ins/del ATTG and TNF-α (-308 G/A) gene polymorphisms on TNF-α serum levels and clinical parameters of sepsis in Turkish sepsis patients." (PMID 28840846, 2018). "For example, it has been demonstrated that myocardial TNF-α expression significantly increases in animal models of LPS or caecal ligation and puncture (CLP)-induced sepsis, and inhibition of p38 or TNF reduces sepsis-induced myocardial dysfunction." (PMID 29615637, 2018). "This mixed early peak in both pro-(IL-6 and TNF) and anti-inflammatory (IL-10) cytokines between time of insult (trauma, hemorrhage, and/or sepsis) and day 1 has been seen in inflammatory stimuli animal models as well as clinical sepsis studies." (PMID 29849508, 2018). "after inducing sepsis by more than 40% (42% in IL-6, 48% in TNF, and 43% in IL-1β levels) (frames (a)-(c))." (PMID 30364002, 2018). "In vivo, treatment with fenoldopam attenuates serum TNF levels in diabetic mice with sepsis by inhibiting splenic TNF production." (PMID 29780390, 2018). "Similar to the dysfunction of blood monocytes, decreased TNFα production in AM of mice and humans with sepsis has been recognized for quite some time." (PMID 30459764, 2018). "Serum TNF-alpha was only detectable in the G-CSF group 12 h after septic insult, whereas various levels of IL-6 were measured throughout the course of sepsis." (PMID 30525057, 2018). "Under pathological conditions of sepsis, a high concentration of NO can activate the NF-κB signaling pathway and induce proinflammatory cytokines (TNF-α, IL-1β, and others)." (PMID 30498752, 2018). "The results from a meta-analysis indicated that the TNF-α-308 single-nucleotide polymorphism (SNP) results in the increased serum TNF levels and the increased risk for sepsis." (PMID 30151394, 2018). "The secretion levels of two major sepsis-related cytokines IL-6 and TNFα were measured by ELISA and showed a marked decrease in the sera of cKO mice compared with the WT mice." (PMID 29352108, 2018). "Inflammatory cytokines, including tumour necrosis factor (TNF)-α, interleukin (IL)-1α, IL-1β, and IL-6, promote the development of sepsis-induced cardiomyopathy." (PMID 29693453, 2018). "This study aimed to assess the ability of mRNA biomarkers (BCL2 and TNFα) to predict patients at risk of HAI, sepsis and MODS, in our community." (PMID 30455877, 2018). "The application of CTCE-0214, a SDF-1α peptide analog and CXCR-4 agonist, significantly suppressed TNF and interleukin (IL)-10 concentrations and improved survival in murine systemic inflammation and sepsis." (PMID 29796010, 2018). "In patients who suffered from sepsis and acute renal failure, continuous veno-venous hemofiltration with dialysis removed TNF-α and IL-1β from systemic circulation." (PMID 29649247, 2018). "It has been reported that the plasma levels of TNF-α are increased in sepsis patients and in animal models." (PMID 30513815, 2018). "Sepsis induces upregulation of multiple proinflammatory genes in the diaphragm, including various proinflammatory cytokines such as TNF-α, IL-1β and IL-6 and there is evidence that these cytokines are involved in sepsis-induced diaphragmatic dysfunction." (PMID 30067847, 2018). "Then, we detected the expression levels of IL-1β, IL-6 and TNF-α in patients with sepsis and healthy subjects to evaluate the influence of the functional IL-27 SNP on the production of these related cytokines." (PMID 30268141, 2018). "Previous studies suggested that TNF-α and IL-1β are involved in the initiation and regulation of inflammatory response; the application of murine monoclonal anti-TNF antibodies induced a transient improvement in ventricular function in patients with sepsis." (PMID 30224945, 2018). "Leukocytes from adult patients with sepsis behave similarly to in vitro endotoxin-tolerised cells, with a reduced responsiveness to produce cytokines, especially TNFα, upon re-challenge with LPS." (PMID 30555806, 2018).
Sepsis (continued). "Some data implied that β-arrestin 2 functions to negatively regulate the inflammatory response (TNF-α) in polymicrobial sepsis." (PMID 29415719, 2018). "GH therapy reduces the levels of CRP in GHD patients, and exerts anti-inflammatory effects in different experimental models of sepsis by lowering TNF-α." (PMID 29346331, 2018). "The failures of anti-toll-like receptor 4 antibody, recombinant activated protein C, and anti-TNF-α therapies in clinical trials require a rethinking of sepsis’ pathophysiology and therapeutic strategies." (PMID 29760707, 2018). "In this study we show that PLD1 is crucial for the TNF-α induced inflammatory response after LPS-induced sepsis in mice thereby regulating TNF-α expression and release, cell survival and thrombin generation and fibrin formation in septic mice." (PMID 29968773, 2018). "Taken together, it is suggested that UTI ameliorates the permeability of pulmonary capillary endothelial cells challenged with sepsis through protection of TJ via inhibiting the TNF-α expression as well as NF-κB and MAPKs phosphorylation." (PMID 30150933, 2018). "Next, we studied how experimental diabetes increases systemic inflammation in sepsis by analyzing TNF production in the organs." (PMID 29780390, 2018). "TNF-α, an early proinflammatory cytokine, is an important mediator for sepsis and concomitant lung injury." (PMID 30627552, 2018). "Our data, for the first time, demonstrated that pilloin reduces IL-6 and TNF-α levels in an LPS-induced sepsis model." (PMID 30513815, 2018). "Regulators of thrombopoiesis, such as thrombopoietin, tumor necrosis factor-α, and interleukin (IL)-6, all increase in patients with sepsis and correlate with sepsis severity." (PMID 29381746, 2018). "Tumor necrosis factor α (TNF-α) promoter polymorphism is related to higher mortality rates and morbidity rates of sepsis." (PMID 30395634, 2018). "In line, only alveolar macrophages of male descendants of sepsis fathers produced less TNF-alpha upon Zymosan stimulation compared to sham descendants, while LPS responses kept unchanged." (PMID 29988283, 2018). "MAPK and NF-κB signal pathways-mediated myocardial TNF-α production and apoptosis contribute to the sepsis-induced myocardial dysfunction." (PMID 29615637, 2018). "After being activated in sepsis, NF-κB increases the expression of proinflammatory cytokines such as nitric oxide, tumor necrosis factor alpha (TNF-α), and interleukin (IL)-1β, and amplifies the inflammatory response." (PMID 30186119, 2018). "Sepsis increased the mRNA expression of the inflammatory markers (TNF-α, IL-1β), but also augmented the expression of TGF-β1, a biomarker of immune disorder." (PMID 30108263, 2018). "Experimental studies of sepsis showed beneficial effects of hyperosmolar solutions modulating inflammatory response, as for instance the expression and release of cytokines TNFα and IL-6." (PMID 29445877, 2018). "In particular, male patients display higher levels of pro-inflammatory cytokines such as IL-6 and TNF-α as well as increased levels of bacteremia markers like procalcitonin in sepsis than females." (PMID 29925409, 2018). "In a matched case-control study in Hinrichs, a combination of three biomarkers– CD3D, IL1B and TNF was the best predictor of post-operative sepsis in an adult cohort of patients, with a specificity of 90% and a sensitivity of 85%." (PMID 30455877, 2018). "Similar to the analysis of phenotypic markers, analysis of cytokine secreting capacity revealed that the condition of cancer and sepsis resulted in an overall decrease in TNF producing cells." (PMID 29338031, 2018). "In contrast, once the acutely harmful clinical event, be it delirium or sepsis is in train, the TNF already released has initiated harmful events, so it is too late to expect to reverse them by neutralizing this cytokine." (PMID 29725287, 2018).